PNPLA4 (patatin like domain 4, phospholipase and triacylglycerol lipase )
Description:
Has abundant triacylglycerol lipase activity. Transfers fatty acid from triglyceride to retinol, hydrolyzes retinylesters, and generates 1,3-diacylglycerol from triglycerides. Additionally possesses acylglycerol transacylase and phospholipase A2 activities. Able to catalyze fatty acyl CoA-dependent retinol esterification during epidermal maturation, when pH becomes acidic.
Synonyms: DXS1283E; GS2; iPLA2eta
Tractability: PROTAC: its protein half-life has been measured.
Gene: Protein-coding gene on chromosome X (7,898,247 to 7,927,739, reverse strand). Ensembl gene ENSG00000006757.
Subcellular location: Mitochondrion
Pathways (Reactome):
Metabolism: Triglyceride catabolism
Gene Ontology:
Molecular function: acylglycerol O-acyltransferase activity; diolein transacylation activity; mono-olein transacylation activity; phospholipase A2 activity; retinyl-palmitate esterase activity; triacylglycerol lipase activity; all-trans-retinyl-palmitate hydrolase, all-trans-retinol forming activity; carboxylesterase activity; catalytic activity; hydrolase activity; retinol O-fatty-acyltransferase activity
Biological process: lipid homeostasis; triglyceride catabolic process; lipid catabolic process; lipid metabolic process; retinol metabolic process
Cellular component: mitochondrion; cytosol; lipid droplet; membrane
Homologues: Orthologues: chimpanzee PNPLA4 (99% identical), dog PNPLA4 (92% identical), guinea pig PNPLA4 (87% identical), pig PNPLA4 (85% identical), macaque PNPLA4 (84% identical), tropical clawed frog pnpla4 (67% identical), rat Pnpla4 (61% identical), zebrafish pnpla4 (61% identical), Caenorhabditis elegans D1054.1 (40% identical). Paralogues in human: PNPLA2 (36% identical), PNPLA3 (33% identical), PNPLA1 (32% identical), PNPLA5 (30% identical).
Diseases named in the same sentence as PNPLA4 in open-access papers:
PNPLA4 is named in the same sentence as 19 diseases in open-access papers, as found by Europe PMC text mining. Sharing a sentence is not in itself a finding about the gene and the disease. The quoted sentences say what the papers report.
Obesity (3 papers, 2009 to 2022). Accumulation of substantial excess body fat. "Therefore, the remarkable elevation of triglyceride levels in patient 1 and obesity in both patients may be associated with loss of PNPLA4." (PMID 32670353, 2020). "Meanwhile, another gene PNPLA4 in the same region was related to human obesity." (PMID 35568907, 2022). "We identified a novel 3,923 kb deletion within the Xp22.31 region (chrX: 5810838–9733877) containing STS, ANOS1, GPR143, NLGN4X, VCX-A, PUDP, and PNPLA4 in patient 1, who presented with KS, XLI, obesity, hyperlipidemia, and strabismus." (PMID 32670353, 2020). "No variants in the PNPLA2, PNPLA4 and PNPLA5 were associated with obesity in this cohort." (PMID 19390624, 2009).
X-linked intellectual disability (2 papers, 2020 to 2023). An X-linked intellectual deficiency in which not enough information is known, reported or published to indicate whether a gene causes non-syndromic or syndromic presentations. "We propose HDHD1 and PNPLA4 for X-linked intellectual disability in this region, since their high transcript levels in the human brain substantiate their role in intellectual functioning." (PMID 31963867, 2020).
anaemia (1 paper, 2023). "Specifically, they implicate PNPLA4 in asthma and anaemia risk in females only, and PNPLA4 in GI disorder risk in males only." (PMID 36379544, 2023). "Nominally significant associations between PNPLA4 and asthma (p=0.040) and anaemia (p=0.013) were noted in females only." (PMID 36379544, 2023). "Genetic analysis indicated significant enrichment of common AF risk variants around STS (7 065 298–7 272 682 bp in GRCh37/hg19 genome build) in males, and of common GI disorder and asthma/anaemia risk variants around PNPLA4 (7 866 804–7 895 780 bp) in males and females, respectively." (PMID 36379544, 2023).
deficiencies (1 paper, 2016). "We newly confirmed 3 mitochondria-related genes (MRPS23, QRSL1, and PNPLA4) as causative genes of mitochondrial respiratory chain complex deficiencies." (PMID 26741492, 2016). "In one such case, we identified PNPLA4 as a novel causative gene for mitochondrial respiratory chain complex deficiencies and proved its mitochondrial localization for the direct evidence of mitochondrial functions." (PMID 26741492, 2016). "We ultimately identified 41 mutations, of which 37 were novel, in 20 genes that were previously reported to cause OXPHOS disease and 3 novel mitochondria-related genes (MRPS23, QRSL1, and PNPLA4) as causative genes of mitochondrial respiratory chain complex deficiencies." (PMID 26741492, 2016).
hyperlipidemia (1 paper, 2020). "Among four cases with deletion of PNPLA4, two patients were obese, and one had fatty liver and hyperlipidemia." (PMID 32670353, 2020).
Intellectual disability (1 paper, 2020). "Patient 2 of Esplin and three CNV patients from Decipher (DCP280938, DCP250671, and DCP251340) involving HDHD1, STS, VCX, PNPLA4 also display intellectual disability." (PMID 31963867, 2020).
liposarcoma (1 paper, 2013). A usually painless malignant tumor that arises from adipose tissue. "For instance, we found a HSPD1-PNPLA4 chRNA in both KPL-4 and SK-BR-3 libraries: PNPLA4 (GS2) is highly expressed in human SW872 liposarcoma cells, while HSPD1, the heat shock protein Hsp60, shows a broad antiapoptotic function in cancer." (PMID 23537109, 2013).
tumor (2 papers, 2015 to 2025). "Importantly, in addition to the aberrant reactivation of genes on the inactive X, aberrant silencing of several genes that normally escape XCI, such as RAB9A, BCOR, RPL39, or PNPLA4 was also observed in tumor cell lines." (PMID 25653311, 2015).
mitochondrial disease (1 paper, 2016). "We identified 3 novel disease-causing mitochondria-related genes (MRPS23, QRSL1, and PNPLA4) as well as other disease-causing genes and novel pathogenic mutations in known mitochondrial disease-causing genes." (PMID 26741492, 2016). "We identified 37 novel mutations in known mitochondrial disease genes and 3 mitochondria-related genes (MRPS23, QRSL1, and PNPLA4) as novel causative genes." (PMID 26741492, 2016).
PNPLA4 also shares sentences with these, for which no sentence is quoted: cancer (2 papers); asthma (1); autism (1); Cognitive impairment (1); developmental delay (1); focal epilepsy (1); ichthyosis (1); OXPHOS disease (1); Strabismus (1); X-linked ocular albinism (1).